INS (insulin)
Diseases named in the same sentence as INS in open-access papers (continued):
Sharing a sentence is not in itself a finding about the gene and the disease.
Hepatic steatosis (continued). "In mice, the genetic deletion of liver MTTP induces hepatic fat accumulation; however, despite hepatic steatosis, these mice demonstrated normal hepatic insulin sensitivity." (PMID 32907986, 2020). "In small randomized, placebo-controlled clinical trials of NAFLD and control patients, resveratrol supplementation had minimal effect on hepatic steatosis, insulin sensitivity, plasma markers of inflammation, and antioxidants." (PMID 33327438, 2020). "We found that ascorbate ameliorated hepatic steatosis induced by excess saturated fatty acid influx through changing cellular lipid profiles as well as improving insulin sensitivity which was related to inhibition of SOCS3." (PMID 32158492, 2020). "In adult men, different authors report goitrogenic effects and a reduction of insulin in non-alcoholic fatty liver patients." (PMID 32824177, 2020). "They measured degrees of severity of fatty liver (FL) from baseline to the end of treatment in the exenatide and intensive insulin therapy groups." (PMID 33664710, 2020). "Studies in mice reveal that inhibition of ceramide synthesis resolves hepatic steatosis and improves insulin-stimulated glucose disposal to slow the progression of cardiometabolic diseases." (PMID 33072120, 2020). "The pathophysiology of NAFLD involves hepatic necroinflammation that develops in the context of hepatic steatosis, lipotoxicity and insulin resistance." (PMID 32151020, 2020). "PGC1α haploinsufficiency in mouse liver inhibits β-oxidation and increases triglyceride synthesis, leading to hepatic steatosis and insulin resistance." (PMID 32660130, 2020). "In another study, linagliptin reportedly improved insulin sensitivity and hepatic steatosis in diet-induced obese (DIO) mice." (PMID 33105604, 2020). "Patients with hepatic steatosis diagnosed by TE had significantly higher serum levels of leptin (P < 0.001), insulin (P = 0.002), HOMA2-IR (P < 0.001) and lower levels of serum adiponectin (P = 0.015) compared to the patients without hepatic steatosis in TE." (PMID 32728230, 2020). "The findings indicate the feasibility of liraglutide treatment combined with basal insulin in attenuating hepatic steatosis and liver injury in ZDF rats." (PMID 33746742, 2020). "Non-alcoholic fatty liver disease (NAFLD) is a spectrum of disorders, ranging from fatty liver to a more insulin resistant, inflammatory and fibrotic state collectively termed non-alcoholic steatohepatitis (NASH)." (PMID 33193105, 2020). "It has been reported that heterozygous KMT2D+/− mice display an altered metabolic phenotype hallmarked by enhanced glucose tolerance, insulin sensitivity, and a higher serum bile acid level, as well as resistance to high-fat diet-induced hepatic steatosis." (PMID 32668765, 2020). "As previously discussed, depleting short-chain ceramides in AT greatly reduces liver steatosis and improves liver insulin sensitivity." (PMID 32887221, 2020). "The greater difference of liver attenuation in obese patients can be attributed to the starting hepatic steatosis condition, which results in a low hepatic attenuation value and uncontrolled glucose overproduction, due to a higher insulin resistance." (PMID 32630032, 2020). "Whilst this manuscript was in revision, Gao and colleagues reported that additional disruption of GPAT3 can improve insulin tolerance and reduce hepatic steatosis in seipin-null mice." (PMID 32094408, 2020). "This is mechanistically plausible as hepatic steatosis occurs (in part) secondary to peripheral insulin resistance and elevated substrate delivery from lipolysis of adipose tissue." (PMID 33108366, 2020). "Oral treatment of rats with age-related hepatic steatosis with β-carotenoid and ZH and D. salina carotenoid fraction for 2 weeks increased the serum adiponectin levels and reduced the serum Apo B and insulin levels as compared with the untreated group." (PMID 32420546, 2020).
Hepatic steatosis (continued). "As previously was reported by Gonzalez-Periz, RvE1 protects against liver steatosis by improving insulin tolerance and induction of PPARγ and adiponectin." (PMID 33266360, 2020). "Amlexanox improved insulin sensitivity, reduced adipose tissue inflammation, increased energy expenditure, and attenuated hepatic steatosis in these obese animal models." (PMID 33193441, 2020). "It has been suggested that NAFLD progresses through multiple “hits” which couple insulin resistance and alterations in adipose tissue lipolysis with increasing efflux of free fatty acids from adipose to the liver resulting in hepatic steatosis." (PMID 33327438, 2020). "The sn-1,2-DAG stereoisomer content was not increased in the plasma membrane from the livers of these mice, explaining the insulin-sensitive hepatic steatosis phenotype." (PMID 32907986, 2020). "TMBIM6 knockout mice, however, featured a higher glucose-stimulated insulin secretion in vivo as assessed by the hyperglycemic clamp test and hepatic steatosis." (PMID 32394396, 2020). "Linagliptin did not inhibit gluconeogenic gene expressions in OSI-906-treated AML-12 cells, consistent with an insulin signaling-independent action of linagliptin on hepatic steatosis." (PMID 33105604, 2020). "The HO-1 pathway plays an important role in the regulation of body weight, adipose tissue expansion, insulin resistance, and hepatic steatosis." (PMID 32751794, 2020). "Accumulating evidence suggests a key role for the cis-unsaturated fatty acid palmitoleic acid (cis-9-hexadecenoic acid; 16:1n-7) in protecting against hepatic steatosis and improving overall insulin sensitivity in metabolic tissues." (PMID 33172033, 2020). "Hepatoma cell lines are widely used to model the hepatocyte for insulin signaling and fatty liver disease." (PMID 32694512, 2020). "Activation of AMPK suppresses hepatic glucose release and enhances insulin sensitivity in dexamethasone-induced fatty liver disease in C57BL/6 mice." (PMID 33204402, 2020). "Secondary outcomes in a subsample include insulin sensitivity, beta-cell function, biomarkers of inflammation and fatty liver disease, quality of life, cognitive function, depressive symptoms and endothelial function." (PMID 32282852, 2020). "HOMA2-S, as a surrogate index of insulin sensitivity, was lower in subjects with fatty liver than in normals." (PMID 31097978, 2019). "Genetic deletion of FXR expression has shown a detrimental impact on lipid profiles, insulin sensitivity and hepatic steatosis." (PMID 31330134, 2019). "There are many CB1R antagonists, including inverse agonists and natural compounds that target CB1R and can reduce body weight, adiposity, and hepatic steatosis, and those that improve insulin sensitivity and reverse leptin resistance." (PMID 31035653, 2019). "For metabolic aspects, research showed that ginsenosides reduced body weight, prevented hepatic steatosis, increased insulin sensitivity, restored mitochondrial dynamics, and attenuated hepatic glucagon response." (PMID 30930854, 2019). "SSE reduced body weight accumulation, improved glucose tolerance and insulin sensitivity and prevented the development of hepatic steatosis." (PMID 31847157, 2019). "Several evidences outline a role of PRDXs in the modulation of hepatic functions: PRDX1 expression was decreased in the liver of HFD-fed mice, PRDX4 transgenic mice were resistant to hepatic steatosis, and insulin resistance increased in response to HFD." (PMID 31949886, 2019). "In fact, a hepatocyte-specific CD36 knockout model demonstrated an attenuation of hepatic steatosis and improved insulin sensitivity." (PMID 31805072, 2019). "Several excellent studies have proven that such metabolites regulate evolution of hepatic steatosis and insulin signaling." (PMID 31555219, 2019).
Hepatic steatosis (continued). "In a family affected by a defect in the AKT serine threonine kinases, which is more distal in insulin signaling, subjects presented severe liver steatosis, altered lipid profile and low adiponectin concentrations." (PMID 31214120, 2019). "In summary, our study illustrated that hepAGT−/− mice exhibited attenuated liver steatosis with improved insulin sensitivity in response to Western diet." (PMID 31604805, 2019). "The evaluation of hepatic steatosis by CAP of the considered sample confirmed the presence of risk factors such as for overweight, increased WC, and increased insulin levels as components of MetS hepatic manifestation." (PMID 31275240, 2019). "Hepatocyte-specific Arg2 overexpression increases basal thermogenesis, enhances insulin sensitivity, and decreases hepatic steatosis and inflammation in genetic and diet-induced models of diabetes and NAFLD." (PMID 30962478, 2019). "PPARγ is involved in regulation of adipogenic differentiation, lipid metabolism, insulin sensitivity and hepatic steatosis." (PMID 30923554, 2019). "Studies in animal models of NASH have shown that GLP-1 therapy improves insulin sensitivity and reduces hepatic glucose production, and can reduce hepatic steatosis, inflammation, steatohepatitis, and fibrosis." (PMID 30605011, 2019). "Generally, an HFD promotes severe changes, such as hepatic steatosis, β oxidation status and the balance of oxidants, which has effects on body weight, insulin signaling and other metabolic parameters." (PMID 31836013, 2019). "Very low calorie diets (VLCDs) are effective at clearing hepatic steatosis and improving insulin sensitivity." (PMID 30464235, 2019). "In mice fed a Western diet, RDX8940, like liraglutide, improved insulin sensitivity and measures of liver steatosis, in line with the previously reported effects of GLP-1 therapy in animal models of NASH." (PMID 30605011, 2019). "Dysregulation of hepatic lipid homeostasis is thought to be important in the development of fatty liver, such as reduced fatty acid oxidation, enhanced de novo lipogenesis, elevated hepatic fatty acid influx, and/or increased systemic insulin resistance." (PMID 31836013, 2019). "Overall, these results demonstrate that targeting CYP4A by HET0016 treatment attenuates hepatic steatosis by ameliorating ER stress and improving insulin signaling in our novel multicellular organotypic liver model." (PMID 31406506, 2019). "In humans, circulating levels of fetuin A are elevated in patients with hepatic steatosis and T2D; moreover, this increase is correlated strongly and negatively with insulin sensitivity." (PMID 31736870, 2019). "This leads to reduced fat mass, improved insulin sensitivity, lower levels of circulating free fatty acids, and less hepatic steatosis in the Ppp1r15a∆C/∆C female mice." (PMID 30814564, 2019). "Other investigational anti-fibrotic agents, such as FGF21 and metformin, display improvement in hepatic steatosis and a decrease in hepatic stiffness by an increase of insulin-sensitization and normalization of serum aminotransferases, respectively." (PMID 30642126, 2019). "It is well known that young mice (10-12 weeks of age) fed a western-type diet (WD) become obese and develop higher cholesterol levels and liver steatosis whereas insulin sensitivity is reduced." (PMID 30860940, 2019). "The consequent reduction in the circulating insulin levels promote adipose-derived fatty acid mobilization to ultimately contribute to hepatic steatosis." (PMID 31546643, 2019). "We demonstrated that hepatocyte glucose transport blockade attenuates insulin resistance and hepatic steatosis in multiple obese models." (PMID 30962478, 2019). "In mouse models, PPARα agonists reduced adiposity, decreased muscle and hepatic steatosis and consequently improved insulin sensitivity." (PMID 29454501, 2019).
Hepatic steatosis (continued). "With the transgenic expression of ceramidase in hepatic and adipose tissue, HFD-fed mice showed reduced systemic ceramide levels, improved insulin sensitivity, and hepatic steatosis." (PMID 31817238, 2019). "It is reported that miRNA-17 family plays a critical role in normal cardiac development, cardiovascular disease and polycystic kidney disease progression as well as affecting hepatic steatosis and insulin signaling." (PMID 31554201, 2019). "A subset of drug responders also exhibited improvements in insulin sensitivity and hepatic steatosis, following a transient increase in serum IL-6 levels." (PMID 30791439, 2019). "To note, hepatic steatosis was related to impaired insulin sensitivity and secretion, leading to the development of metabolic alterations." (PMID 31428049, 2019). "It has been previously reported that AMP-dNM treatment improves glucose tolerance, reduces hepatic steatosis, and enhances insulin response in rodent models of type 2 diabetes." (PMID 31852956, 2019). "Together, these data indicate that FoxO3 overexpression aggravates hepatic steatosis and reduces glucose tolerance and insulin sensitivity in mice fed a high-fat diet." (PMID 31729980, 2019). "After 3–4 months on FF, hepatic steatosis was evident although indices of glucose tolerance and insulin sensitivity were minimally affected." (PMID 31510077, 2019). "In this study, we demonstrated that dietary HMCA was efficacious against HFD-induced weight gain and hepatic steatosis, and that it improved insulin sensitivity." (PMID 31075850, 2019). "Whereas PTEN-knockout mice gained more adipose tissue during HFD feeding, they showed enhanced insulin sensitivity, improved hepatic steatosis, and reduced adipose tissue inflammation." (PMID 31234839, 2019). "Our data strongly suggest that IRA is more efficient than IRB at favoring hepatic glucose uptake, improving insulin tolerance and ameliorating hepatic steatosis." (PMID 30642871, 2019). "Attenuation of ROS and inflammation significantly contributed to the improvement of insulin sensitivity and suppression of hepatic steatosis." (PMID 31887984, 2019). "Second, patients and cows with NASH both display high NEFA levels, hepatic steatosis, hepatic insulin resistance, oxidative stress and inflammation." (PMID 29602237, 2018). "The restoration of Bscl2 expression selectively in adipocytes of Bscl2 knockout mice not only prevents lipodystrophy, but also insulin resistance and hepatic steatosis." (PMID 29459250, 2018). "Glucose and insulin levels, surrogate estimates of insulin sensitivity, and hepatic steatosis through ultrasonography and HSI were evaluated." (PMID 30662461, 2018). "Reduced hepatic steatosis along with increased hepatic insulin sensitivity and fatty acid oxidation can promote apolipoprotein B degradation, thereby contributing to lowering the secretion of LDL and LDL particle and circulating cholesterol level." (PMID 30327679, 2018). "High-fat-diet (HFD)-fed AKO mice exhibited increased adiposity and exacerbated hepatic steatosis and fibrosis and impaired glucose tolerance and insulin sensitivity." (PMID 29515462, 2018). "As a main component of DZF, berberine has the hypoglycemic, hypolipidemic, and insulin sensitizing effect, attenuating hepatic steatosis, and activates AMPK and GLUT4 in the skeletal muscle." (PMID 29593575, 2018). "In conclusion, DZF, as a TCM herbal formula containing berberine, naringin, and other components, exhibits a prominent effect in improving insulin sensitivity, hepatic steatosis, and skeletal muscle energy metabolism in db/db mice." (PMID 29593575, 2018). "The increase of FGF21 expression by CO is associated with alleviating metabolic disorders, including improving glucose tolerance and insulin sensitivity and in ameliorating hepatic steatosis and adipose tissue dysfunction." (PMID 29295856, 2018).
Hepatic steatosis (continued). "Gluconeogenesis overstimulation due to hepatic insulin resistance is the best-known mechanism behind elevated glycemia in obese subjects with hepatic steatosis." (PMID 30360555, 2018). "It has been postulated that HIV infection can induce hepatic steatosis, either through the effects of immune activation on insulin tolerance and lipogenesis, or indirectly—through metabolic abnormalities and toxicity of antiretroviral therapy." (PMID 30505292, 2018). "Because the manifestation of hepatic steatosis is usually accompanied by a constellation of adverse alterations in glucose metabolism, we conducted glucose tolerance and insulin resistance tests." (PMID 30566427, 2018). "This was followed by decreased hepatic steatosis, systemic and adipose tissue inflammation and increased insulin sensitivity after three months." (PMID 30333571, 2018). "In summary, MLE-supplemented db/db mice had not only lowered blood glucose and insulin but also decreased TG and TC levels, and improvements in IR and fatty liver." (PMID 30150922, 2018). "The induction of hepatic steatosis was achieved using both free fatty acids as well as a combination with monosaccharides and insulin." (PMID 30250238, 2018). "Insulin signaling was attenuated in the liver and adipose tissues of macrophage-specific Atg7KO mice, accompanied with improvement of hepatic steatosis." (PMID 30123267, 2018). "Our work suggests that vildagliptin increased hepatic insulin sensitivity by preventing hepatic steatosis, and our results imply the possible involvement of the DDP-4 inhibitor vildagliptin in the complex interplay in the improvement of hepatic steatosis." (PMID 29721506, 2018). "Ion transport has been associated with oxidative stress and plays an important role in the progression of liver steatosis to insulin insensitivity and more severe conditions such as hepatocellular carcinoma." (PMID 30343673, 2018). "The beneficial effects of BBR on insulin sensitivity and hepatic steatosis show promise in the treatment of metabolic disorders, such as hyperlipidemia and diabetic rats." (PMID 29882814, 2018). "In summary, our results reveal a novel effect of EA, whereby it reduces hepatic steatosis and oxidative stress, and improves insulin sensitivity." (PMID 29693586, 2018). "Revised quantitative insulin sensitivity check index (RQUICKI) of cows with fatty liver was significantly lower than that of healthy cows." (PMID 29882814, 2018). "It has been reported that C16:1n7-palmitoleate acts as an adipose tissue-derived lipid hormone that strongly stimulates the action of insulin in muscle and suppresses hepatic steatosis." (PMID 29681853, 2018). "We found that P465L mice have increased levels of insulin and FFA, both risk factors associated with fatty liver." (PMID 29790245, 2018). "Genetic deficiency of CD40L in diet-induced obesity (DIO) ameliorates adipose tissue inflammation, hepatic steatosis and increases insulin sensitivity." (PMID 30096208, 2018). "The mechanism of the development of a fatty liver is explained by the insulin resistance that activates lipolysis, resulting in the accumulation of non-esterified fatty acids." (PMID 30697502, 2018). "Tmprss6−/− mice show a significant decrease in body fat, improved glucose tolerance and insulin sensitivity, and are protected against hepatic steatosis." (PMID 29636509, 2018). "The mice showed enhanced insulin sensitivity, improved hepatic steatosis, and reduced adipose tissue inflammation, which were consistent with this study." (PMID 30382157, 2018). "Leucine improved glucose tolerance, decreased hepatic steatosis, and decreased inflammation in adipose tissue in mice fad a high-fat diet and rescued insulin signaling in adipose tissue obtained from insulin resistant db/db mice." (PMID 29755574, 2018). "Sirt1 transgenic mice show better glucose tolerance and insulin sensitivity and are almost entirely protected from hepatic steatosis with HFD treatment." (PMID 30574122, 2018).